RN7SL733P (RNA, 7SL, cytoplasmic 733, pseudogene)
Gene: Miscellaneous RNA gene on chromosome 10 (87,154,041 to 87,154,369, reverse strand). Ensembl gene ENSG00000273946.
Homologues: Orthologues: macaque Metazoa_SRP (96% identical), chimpanzee Metazoa_SRP (76% identical). Paralogues in human: RN7SL248P (98% identical), RN7SL453P (98% identical), RN7SL33P (70% identical), RN7SL487P (69% identical), RN7SL775P (69% identical), RN7SL40P (67% identical), RN7SL1 (66% identical), RN7SL526P (66% identical), RN7SL2 (66% identical), RN7SL317P (66% identical), RN7SL3 (66% identical), Metazoa_SRP (65% identical), and 701 more.